ERBB2 (erb-b2 receptor tyrosine kinase 2)
Diseases named in the same sentence as ERBB2 in open-access papers (continued):
Sharing a sentence is not in itself a finding about the gene and the disease.
tumor (continued). "Results showed that ERBB2 and TOP2α gene status are highly correlated (r=0.87, p<0.0001, n=25), with few tumor samples presenting amplification." (PMID 31301170, 2019). "High Content Screening (HCS) fluorescence imaging showed that, upon binding, both trastuzumab and ST8176AA1 are rapidly internalized by ErbB2-expressing tumor cells and are both localized within the cytoplasm." (PMID 32039017, 2019). "Swiercz's study indicated Plexin-B1 stimulated tumor cell migration via tyrosine kinase receptor ErbB-2 pathway while antimigrated via met pathway, He believed that the effect of SEMA4D/Plexin-B1 mainly depended on the superior pathway." (PMID 30762724, 2019). "Abundance of our three key proteins INPP4B, CDK1, and ERBB2 across tumors of different ER status, tumor grade, and HER2 status correlated well with their respective transcript levels." (PMID 31315058, 2019). "YY1-dependent transcriptional activation and repression of ERBB2 and p27 respectively, leads to tumor promotion." (PMID 31824839, 2019). "The locus containing the ERBB2 gene on chromosome 17 in the PH026 tumors also showed a number of alterations present in both the original tumor and the PDX." (PMID 30499260, 2019). "Together, these data indicate that DFTD tumor cells, which express high levels of phosphorylated ERBB2 and ERBB3 and show activation of the ERBB signaling pathway, are exquisitely vulnerable to ERBB kinase inhibitors." (PMID 30645971, 2019). "It has been reported that in OEC, autologous DCs loaded with ovarian-associated antigens (ErbB2, MUC-1, and CA-125) were able to stimulate the proliferation of autologous T cells and to induce tumor-specific cytotoxic activity." (PMID 31886313, 2019). "The samples show a difference in the ERBB2 amplicon size, CN and structure, suggesting that sample p-103 is a second primary tumor." (PMID 31827209, 2019). "Lapatinib exhibited cytotoxic properties on ErbB1/ErbB2 expressing cell lines, with intestinal cells being more sensitive to lapatinib compared to tumour cells." (PMID 31905843, 2019). "Inhibition of ErbB2-dependent proliferation of 32D_B2/B3 cells as well as inhibition of ErbB2-expressing tumor cell growth by ST8176AA1 was higher than that obtained with trastuzumab as measured by CellTiter-Glo Luminescent Cell Viability assay." (PMID 32039017, 2019). "The human epidermal growth factor receptor 2 [(HER2), ErbB2] stimulates tumor cell proliferation via the Ras-MAP-kinase pathway and its expression is often associated with an aggressive tumor phenotype, advanced stage diseases, and poor clinical outcome." (PMID 29725336, 2018). "In previous studies, we defined the comprehensive downstream changes upon inhibition of oncogenic EGFR/ErbB2 in EGFR/ErbB2-addicted tumor models and identified a very select number of genes altered as early as 6 hours following EGFR/ErbB2 blockade." (PMID 29861842, 2018). "In agreement with previous studies, the tumor type that most frequently showed ERBB2 alteration was GC (25% of cases)." (PMID 29854313, 2018). "We found that ganetespib remarkably inhibited ErbB2-overexpressing tumor growth with an average final tumor volume of 922.8 ± 291.7 mm3 in the ganetespib-treated mice versus 2848.6 ± 489.6 mm3 in the control mice." (PMID 29717218, 2018). "In particular mutations in ERBB2, PTPRD, PTPRT, AURKB correlated with at least one of the clinical-pathological parameters under analysis such as node status (N), stage, tumor size (T) and/or presence of metastasis (M1)." (PMID 29844865, 2018). "Recently, we demonstrated that anti-erbB2/neu targeted antibody can promote the development of tumor specific CD8+ T cells in a syngeneic MMTV-neu mouse model." (PMID 29423071, 2018). "ERBB2 genomic alterations were diffuse across metastatic tumor types and signs of efficacy emerged for HER2 targeted treatments, especially in case of ERBB2 amplifications or a p.S310Y ERBB2 mutation." (PMID 29515767, 2018).
tumor (continued). "Analysis of the CNAs demonstrated that ERBB2 amplification was present both in the primary tumor and all brain metastases; reinforcing its role as an early ‘truncal’ event." (PMID 29755676, 2018). "Kindlin-3 expressed by tumor infiltrating immune cells, was more prominent in triple-negative and ERBB2 tumors, those subtypes shown to exhibit a higher number of TILs." (PMID 30477537, 2018). "We have observed responses for patients with tumor types other than oesogastric or breast and ERBB2 amplifications." (PMID 29515767, 2018). "Concurrent use of trastuzumab and CON can overcome chemoradiation resistance conferred by erbB2 overexpression and tumor hypoxia." (PMID 30223570, 2018). "The most frequently mutated genes across all tumor types included KRAS (30 patients), PIK3CA (16 patients), BRAF (6 patients), EGFR (5 patients), NRAS (4 patients), and ERBB2 (3 patients)." (PMID 29854313, 2018). "The most frequently mutated genes across all tumor types included KRAS, PIK3CA, BRAF, EGFR, NRAS and ERBB2." (PMID 29854313, 2018). "ERBB2 expression was significantly higher in a subset of tumor samples, consistent with the frequent amplifications observed in various tumor types." (PMID 29664468, 2018). "Large cohorts of patients, multi histology basket trials or tumor agnostic meta-analysis would be required to clarify the algorithm of treatment decision in case of ERBB2 and ERBB3 alterations, based on previous preclinical and clinical data available." (PMID 29515767, 2018). "Upon the termination of the experiment, ~20 days following cells injection, the tumors were dissected and tumor lysates were used to determine ErbB2 and Erk activation (phosphorylation) levels using western-blot analysis." (PMID 29352243, 2018). "The most common mutation detected in primary tumor tissues was PIK3CA (6 patients, 37.5%), followed by ERBB2, mTOR and INPP4B (5 patients for each one, 31.25%)." (PMID 30167082, 2018). "ErbB2 blocks tumor cell anoikis by triggering a complex and poorly understood network of the antiapoptotic signals." (PMID 30545388, 2018). "A combination of cerulenin and trastuzumab synergistically downregulates ErbB2 expression, leading to more effective inhibition of tumor growth." (PMID 29700319, 2018). "Activation of downstream pathways of RTKs, such as ERBB2, EGFR, and IGF1R, has been proven to be related to tumor cell anoikis resistance, and IBC cells have been associated with more evasion of anoikis which is consistent with our findings." (PMID 30086764, 2018). "Concurrent use of trastuzumab and a combination of carbogen and nicotinamide can overcome chemoradiation resistance conferred by erbB2 overexpression and tumor hypoxia." (PMID 30223570, 2018). "Two histological tumor types in which ERBB2 amplification has a similar impact on proteins are breast (BRCA) and gastric (STAD) cancers (p = 2.3e−3)." (PMID 30442178, 2018). "Utilising a multivariate analysis, only five conditions were needed to stratify OS of these basal-like tumours, miR-29b-1-5p, age at diagnosis, lymph node status, ERBB2 (HER) and miR-664." (PMID 30323900, 2018). "Alternatives to syngeneic mouse cell lines are tumour-prone genetically modified mice, such as those expressing a polyoma middle T (PyMT) or ErbB2/neu transgene in the mammary gland." (PMID 29208627, 2018). "Co-culturing of ErbB2 tumor cells with activated T cells induced a significant increase in Gbp1 expression by the cancer cells." (PMID 29350274, 2018). "MSC-AR properties were tested in human ovarian carcinoma cell line SKOV3ip1 and in vivo using transient transgenic mice that express human erbB2 in the ovarian xenograft tumour model." (PMID 29966369, 2018). "ERBB3 has been reported as highly expressed in TGCT tumours with signal activation dependent on ERBB2 activation with which it forms heterodimers." (PMID 29160922, 2018).
tumor (continued). "For example, transgenic CD4+ lymphocytes that recognize a mutant tumor-specific neoantigen ERBB2 protein induced sustained tumor regression in a patient with cholangiocarcinoma." (PMID 28108950, 2018). "Comparison of gene expression in non-tumor bearing control ErbB2;Ptenfl/fl and experimental ErbB2;Fsp-cre;Ptenfl/fl mice uncovered a defect in DNA repair in pre-neoplastic ductal luminal epithelium of mammary glands lacking stromal PTEN." (PMID 30018330, 2018). "We have previously demonstrated that in primary FLC tumor tissue there are consistent changes in various oncologically relevant pathways such as EGF/ErbB2, Aurora Kinase A and wnt signaling pathways." (PMID 29535801, 2018). "Analyzing MLPA results we found 17 tumor samples with the ERBB2 gene amplification which accounts for about 24 % of all samples." (PMID 29743853, 2018). "IKKα is also an important contributor to ErbB2-induced oncogenesis, as it supports the expansion of tumor-initiating cells from premalignant ErbB2-expressing mammary glands." (PMID 28587092, 2017). "Most known oncogenes (e.g. EGFR, FGFR1, MYC, ERBB2) or tumor suppressors (e.g. CDKN2A, NOTCH1) were detected to reside within the focal SCNA regions." (PMID 29348864, 2017). "Unexpectedly, the combination of AR42, but not sodium valproate, with checkpoint immunotherapies activated both ERBB1 and ERBB2 in the surviving tumor cells." (PMID 29137331, 2017). "Overall data in ErbB2+ tumor cells point to the induction of apoptosis and inhibition of apoptosis resistance by AvidinOX-anchored bTrast or bPert." (PMID 28186982, 2017). "Because ERBB2 copy numbers are extensively heterogeneous between individual tumor cells, BFB cycles are a strong candidate for the underlying mechanism." (PMID 28211519, 2017). "Carcinoma cells from the HER2+ (HER2; BC04 and BC06) and ER+HER2+ (luminal B; BC03) tumours expressed high levels of the ERBB2/HER2 gene and genes located in the HER2 amplification region on chromosome 17q11-25." (PMID 28474673, 2017). "All these data show that p140Cap dampens tumour features, affecting tumour growth, sensitivity to apoptosis and metastatic properties of ERBB2-positive cancer cells." (PMID 28300085, 2017). "EGCG was proved to inhibit the tumor growth and the activation of ErbB1, ErbB2, and ErbB3 which are expressed in many different human cancer lines." (PMID 28286519, 2017). "Our results suggest that tumor cells with lower Mek activity produce lower ErbB2 amounts than those with a higher Mek activity." (PMID 29285258, 2017). "ErbB3 predominantly forms a heterodimer with ErbB2 and was found to be critically involved in tumour initiation and progression and is now considered one of the most active signalling dimers of the ErbB family in cancer." (PMID 28417948, 2017). "In conclusion, our data are consistent with p140Cap exerting a suppressive function on ERBB2 oncogenic features and with it having a regulatory impact on molecular pathways that ERBB2 exploits for tumour progression." (PMID 28300085, 2017). "A tumor was considered HER2 positive if IHC 2+ staining was observed in ≥ 10% of tumor cells and ERBB2 was amplified (ERBB2/CEN17 ratio ≥ 2 or nERBB2 ≥ 4)." (PMID 28388586, 2017). "ESR1 (ER), PGR (PR), ERBB2 (HER2) gene expression values tended to be homogeneous across different tumor regions, while MKI67 mRNA levels are slightly varying between regions." (PMID 29187174, 2017). "We recommend future studies should focus on in vivo cytotoxicity of CAR-T cells against ERBB2 expressing tumours." (PMID 28885562, 2017). "Overall, the results point to the ability of p140Cap to counteract the EMT invasive program of ERBB2 tumour cells." (PMID 28300085, 2017).
tumor (continued). "Mutations in the RTK genes involving EGFR, ERBB2, ERBB4, FLT1 and EPHA/B, were identified in 5/7 (71%) of the H3/IDH1 wildtype tumor pairs." (PMID 29084603, 2017). "Altogether, our results argue for a key role of p140Cap in curbing the aggressiveness of the ERBB2 tumours, counteracting in vivo tumour growth, epithelial mesenchymal transition and metastatic lesions." (PMID 28300085, 2017). "p140Cap dampens ERBB2-positive tumour cell progression, impairing tumour onset and growth in the NeuT mouse model, and counteracting epithelial mesenchymal transition, resulting in decreased metastasis formation." (PMID 28300085, 2017). "Gains and focal amplifications affected both mRNA and protein levels significantly (p = 10−16 and p = 10−5, respectively), however, only 34% of the tumors with ERBB2 IHC TCS staining ≥ 2 (Tumor Cell Score) had ERBB2 copy number gains detectable with array-CGH." (PMID 28388586, 2017). "The tested mutations are from four genes, including two tumor suppressors (TGFBR1 and CHEK2) and two oncogenes (KDR and ERBB2)." (PMID 28743916, 2017). "Proliferation of the dual MUC1/ErbB2 CAR T cells required coexpression of MUC1 and ErbB2 on target tumor cells, and the CAR T cells were effective in killing ErbB2(+) tumor cells." (PMID 29312333, 2017). "The ErbB family receptors, including EGFR (ErbB1), HER2 (ErbB2), HER3 and HER4 are most frequently implicated in neoplasia and are known to turn on the PI3K/AKT pathway to regulate cell proliferation, survival, angiogenesis, migration and invasion." (PMID 29066975, 2017). "The ErbB2 peptide cleared renally with minimal biodistribution outside of the tumor to suggest a safe toxicity profile." (PMID 29089571, 2017). "Our data demonstrate that overexpression of HCaRG inhibits RCC development and tumor angiogenesis by inactivating the proto-oncogene, ErbB2, and gene silencing of EGFR and ErbB3." (PMID 29050225, 2017). "Consistently, we found that ErbB2 inhibition by lapatinib not only strongly suppressed tumor progression in ErbB2 mice, but does so, at least in part, via inactivation of HSF1." (PMID 27791982, 2017). "Decades of scientific study links the overexpression of human epidermal growth factor receptor 2 (ERBB2) antigen with aggressive tumours." (PMID 28885562, 2017). "Taken together, these data show that p140Cap interferes with the Rac circuitries that control ERBB2 tumour progression, by binding to Tiam1, leading to both Tiam1 and Rac inactivation." (PMID 28300085, 2017). "Only one of 43 OCCC tumors (2%) showed overexpression and amplification of ERBB2, and one tumor displayed amplification (ratio ≥ 2) with weak protein expression (1+)." (PMID 28611940, 2017). "To understand the underlying mechanisms of phenformin-induced inhibition of tumor growth and EMT, we first examined the effects of phenformin on the ErbB2 signaling pathway, which is the driving force behind the oncogenicity of these tumors." (PMID 28947975, 2017). "In contrast, ErbB2-CAR CIK cells infiltrated the tumor spheroids within the first 24 hours of co-culture." (PMID 29029499, 2017). "Nowadays, immuno-histochemical (IHC) staining techniques are widely used to obtain a semi-quantitative estimation of ERBB2 in tumor tissues." (PMID 28817097, 2017). "Immunohistochemical analysis of the tissue micro array derived from these patients established the functional correlation between the decreased expression of tumor suppressive miRNAs and their target oncogenes: ERBB2, EGFR, EPHA2, BAX, GNA12, GNA13, and JUN." (PMID 28740575, 2017). "In 2000, the FDA approved and certified 15 ng/mL is the upper limit of ERBB2 in the serum of healthy subjects, thus pushing the medical community to use such a value as a reliable indicator of anti-tumor treatment efficiency." (PMID 28817097, 2017). "The ErbB2 overexpressing model showed significant tumour regression upon treatment indicating the tumour’s addiction to ErbB2 signalling." (PMID 28417948, 2017).
tumor (continued). "GLS1 was also reported to be regulated by series of oncogene or tumor-suppressors including Rho GTPase, ERBB2, EGFR, most have bearing on transcriptive regulation." (PMID 27902968, 2017). "Down-modulation of growth factor receptors is a key mechanism for controlling the growth of tumor cells and among the receptors, ErbB2 exhibits the peculiar property to be resistant to down-modulation and to antibody-dependent ErbB2 degradation." (PMID 28186982, 2017). "In this context, we also demonstrate that miR-23b is a tumor suppressor miRNA in p130Cas/ErbB2 cells and that Blimp1 expression downmodulation is critical for miR-23b-dependent cell invasion impairment." (PMID 28442738, 2017). "We tested eleven distinct mutations in several genes, including the oncogenes ERBB2 and VEGFR2 and the tumor suppressors CHEK2 and TGFBR1." (PMID 28743916, 2017). "Present data show for the first time that, in the presence of AvidinOX, low concentrations of a single anti-ErbB2 antibody can exhibit similar anti-tumor potency as that of high concentration antibody mixtures reported in the literature." (PMID 28186982, 2017). "Present data show inhibition of tumor cell proliferation and signaling, induction of apoptosis and down-modulation of ErbB2 in tumor cells treated with AvidinOX and either bTrast or bPert." (PMID 28186982, 2017). "It was constructed as a fusion between a human RNase and an anti-ErbB2 human scFv, shown to be a potent killer of ErbB2-expressing cells in vitro and to inhibit the growth of human tumor xenografts in nude mice." (PMID 28574434, 2017). "The analysis of 200 ERBB2-amplified tumours from a large Swedish Cohort8, showed that the SRCIN1 gene is altered in 70% of cases, with 123 cases (61.5% of the total) showing a copy number (CN) gain for SRCIN1." (PMID 28300085, 2017). "First, we found that only one of the three tumours with ERBB2/HER2 amplification had prominent activation of the HER2 downstream signalling pathway." (PMID 28474673, 2017). "ERBB2, ERBB3 and SYK were functionally more active overall in tumors and TYRO3 was more active in paired tumor samples and also mutated on kinase gene sequencing." (PMID 28423512, 2017). "Estrogen and progesterone receptor (ER and PR), HER2/ERBB2, and Ki67 expression levels together with tumor–node-metastasis (TNM) staging are the parameters used to stratify patients and guide therapeutic decisions." (PMID 26527623, 2016). "Even though all IBC patients were HER2-positive via IHC or FISH, only 16 of 20 tumours were called as having ERBB2 amplification; two tumours (IBC011 and IBC029) harboured gains and two tumours (IBC007 and IBC028) had neither amplification nor gain of ERBB2." (PMID 27923043, 2016). "The potential role of semaphorin signalling to an ErbB2/Nrp1 receptor in cancer cells and tumour vasculature will be an interesting focus of future studies." (PMID 27356767, 2016). "New therapeutic agents targeting the endocytic recycling and intracellular trafficking of membrane in tumor cells overexpressing ErbB2 are actually in clinical development." (PMID 26716506, 2016). "This is based on data showing ErbB2-driven tumor arrest and senescence in vivo in response to acute cyclin D1 ablation or targeted inhibition of CDK4/6." (PMID 26857361, 2016). "Molecular and clinical studies indicate that ErbB2 has important implications in tumor etiology and progression." (PMID 26716506, 2016). "Other selected targets in clinical trials for CAR T cell therapy, an approach that also requires highly tumor-specific targets, include ERBB2, mucin-16 (MUC16), prominin 1 (PROM1) and the prolyl endopeptidase FAP (FAP)." (PMID 26700623, 2016).